NOD1 (nucleotide binding oligomerization domain containing 1)
Diseases named in the same sentence as NOD1 in open-access papers (continued):
Sharing a sentence is not in itself a finding about the gene and the disease.
cancer (continued). "The regulation of NLR and RLR‐driven NF‐κB signalling by E3 ligases has not been clearly described in cancer; however, a few studies have demonstrated the cancer implication of E3 ligase regulation of NOD1/2‐driven NF‐κB signalling." (PMID 36881608, 2023). "Interestingly, our study also revealed hub genes (MEG3, MIAT, IRF1, ADAMTS9-AS2, TP63, NOD2, NOD1, NLRP3, MAGI2-AS3, and PVT1, respectively) within the pyroptosis-related ceRNA network, some of which have been well-studied in the field of cancer biology." (PMID 37511974, 2023). "Next, we showed that our most potent NOD1 agonist SZZ-38 markedly enhanced the LPS-induced cytokine secretion from PBMCs, in addition to PBMC- and natural killer (NK) cell-mediated killing of K562 cancer cells." (PMID 35935855, 2022). "In addition, according to the Cancer Cell Line Encyclopedia (CCLE) database, the expression levels of NOD1 and NOD2 in PC cell lines are generally very low." (PMID 35115556, 2022). "Herein, we postulate that stimulation of NOD1 alone or a combined stimulation of NOD1 and TLR4 could also strengthen PBMC-mediated cytotoxicity against cancer cells." (PMID 35935855, 2022). "Next, a flow cytometry-based PBMC cytotoxicity assay was utilized to delineate whether either stimulation of NOD1 alone or a combined stimulation of NOD1 and TLR4 can strengthen the cytolytic activity of PBMCs and NK cells against K562 cancer cells." (PMID 35935855, 2022). "C12 stimulation of Sh4-HT29 cancer cells, which was used as a negative control as this construct elicited the same NOD1 protein expression as non-treated controls, a phenotype as adhesive as wildtype + C12 was observed." (PMID 31956962, 2020). "The cytosolic nucleotide‐binding oligomerization domains 1 and 2 receptors (NOD1 and NOD2) are important components of the innate immune system and constitute interesting targets in terms of strengthening the immune response against cancer cells." (PMID 30548868, 2019). "Notably, the E3 ligase “dead mutation” of MARCH7 failed to reverse the tumorigenic effects of NOD1 in xenograft tumors, as well as the expression of proteins involved in cancer stemness, proliferation, and invasion." (PMID 38462600, 2024). "Although the present study gives important new insights into the potential crosstalk between NOD1, IL-10-induced STAT1-STAT3 signalling and SOCS protein functions in haematopoietic cells, potential relationships amongst these proteins in the context of cancer need to be further investigated." (PMID 28432285, 2017).
bacterial infection (56 papers, 2008 to 2026). "Further analyses on the association between NOD1 polymorphisms and the resistance to infectious diseases, particularly bacterial infections, are expected to elucidate the possible contribution of NOD1 polymorphisms to disease susceptibility." (PMID 34573406, 2021). "These and our results suggest that alterations in the UPR render intestinal cells more susceptible to bacterial infections in a NOD1/2-dependent manner, causing aberrant intestinal inflammation." (PMID 31109951, 2019). "For example, Lysenko and colleagues demonstrated that NOD1 is crucial to neutrophil-mediated clearance of bacterial infection in vivo and that opsonophagocytic killing of bacteria in vitro is significantly reduced in NOD1-deficient neutrophils." (PMID 25922834, 2015). "Besides sensing of bacteria, NOD1 has also been proposed as a sensor of small GTPase activity and F-actin perturbation, caused by bacterial infections." (PMID 33525590, 2021). "Upon viral infection, induction of RIPK2-dependent NOD1 signaling might be of physiological importance for the higher lethality and morbidity associated with secondary bacterial infection." (PMID 33525590, 2021). "However, it seems clear that Nod1-deficient mice are more susceptible to bacterial infections such as Clostridium difficile and Nod1 is important for the interaction of S. Typhimurium with dendritic cells." (PMID 25423082, 2014). "Activation of NOD1 and NOD2 induces autophagy in response to pure microbe-associated molecular patterns (MAMPs) as well as bacterial infections such as Listeria monocytogenes and Shigella spp." (PMID 37519301, 2023). "Studies on RIP2 have focused on its mediation of inflammatory reactions to bacterial infections (through the NOD1/2-signaling), or involvement in response to certain RNA virus infections, and DNA damage." (PMID 37223098, 2023). "RIP2 is a pivotal regulator of inflammatory responses to bacterial infections, where it is activated by the NOD1 and NOD2." (PMID 38012669, 2023). "The ALPK1-TIFA-mediated pathogen recognition system is thought to play a role in supporting a sustained inflammatory response during the later stages of bacterial infection after the initial transient NOD1-mediated NF-κB activation." (PMID 37519301, 2023). "Viral infection augments signaling through NOD1/NOD2 pathways to oppose secondary bacterial infection." (PMID 34573406, 2021). "For example, Jonathan and colleagues showed that the activation of the CaSR/PLC/IP3R signaling pathway increases NOD1 inflammatory responses after bacterial infections." (PMID 34603302, 2021). "In fish, two tlr5 genes (tlr5M and tlr5S) and nod1 mRNAs were up-regulated notably after bacterial infection." (PMID 33732247, 2021). "Taken together, our results reveal that NARL in fish is a critical positive regulator of innate immune responses to viral and bacterial infection by suppressing a feedback to NOD1-NF-κB/IRF3-mediated signaling." (PMID 33581111, 2021). "During bacterial infection, NOD1 recognizes foreign bacterial DNA and activates NF-κB via the signaling adaptor protein RIP2 and IKK complexes, thereby inducing the production of pro-inflammatory cytokines." (PMID 30717343, 2019). "Together, these results suggest that differential UPR activation makes cells more responsive to bacterial infections in a NOD1-dependent manner." (PMID 31109951, 2019). "It plays an important function in recognizing intracellular bacterial infection through regulating and transducing NOD1 and NOD2 signaling." (PMID 29874851, 2018). "Nod1/2-Rip2 signaling, which is essential for initiating the innate immune response to bacterial infection and ER stress, is subject to many regulatory mechanisms." (PMID 27830463, 2017). "The intracellular pathogen Shigella flexneri was the first shown to activate a cytosolic receptor known as CARD4 (Nod1), which detects PG fragments generated by both intracellular and extracellular bacterial infections." (PMID 29042497, 2017).
bacterial infection (continued). "Moreover, intracellular proteins NOD2 and NOD1 exert critical effects on autophagy induction upon bacterial invasion by recruiting ATG16L1 proteins to the site of bacterial infection on cell membrane." (PMID 32940422, 2020). "In addition, ER stress, which occurs during certain bacterial infections, induces inflammation in a Nod1-, Nod2-, and Rip2-dependent manner." (PMID 27830463, 2017). "Moreover, the use of Nod1−/− and Nod2−/− mice supported the key role of these molecules in restricting bacterial infection." (PMID 23162548, 2012). "However, bacterial infections can activate multiple accessory pathways; for example, the receptors NOD1/2, TLR9, and DAI can all be activated in response to bacterial challenge." (PMID 20657826, 2010). "Finally, very recent evidence suggests that NOD1 and NOD2 are essential for recruitment of ATG16L1 during bacterial infection, which is impaired in patients with CD-associated NOD mutants." (PMID 21209938, 2010). "Activation of either NOD1 or NOD2 activates TAK1, leading us to hypothesize that during bacterial infection, XIAP may facilitate this key association, linking cytosolic sensors to downstream signaling mediators." (PMID 18769721, 2008). "Therefore, it was found that fish NOD1 can recognize LPS and iE-DAP and eventually causes an inflammatory response that could elucidate the resistance of fish against bacterial infections." (PMID 33581111, 2021). "Thus, NOD1 shows unparalleled importance in the resistance against bacterial infections in fish." (PMID 30013548, 2018). "NOD1 and NOD2, founding members of the NOD-like receptor (NLR) family, play a crucial role in host defense against bacterial infections." (PMID 42213708, 2026). "In the case of specialized forms of autophagy, including xenophagy and mitophagy, nucleotide binding oligomerization domain containing 1 (NOD1) and NOD2 can begin autophagy through direct interaction with ATG16L1 upon detection of bacterial infection." (PMID 37397491, 2023). "RIPK2, also known as RIP2, is a protein used by NOD1 and NOD2 to direct the innate immune response against viral and bacterial infections." (PMID 36733771, 2022). "Based on this and our study, it is possible that piscine BIRC2 is involved in the regulation of immune responses mediated by NOD1 and NOD2 signaling in response to bacterial infection." (PMID 34887869, 2021). "It is published before the NOD1 and NOD2 and their adaptor serine-threonine kinase RICK: kinase (Rip2) were related to immune responses induced by bacterial infection." (PMID 34812410, 2021). "At present, this makes no sense from any existing perspective, since RIG1 should be either upregulated or downregulated by any viral infection, and NOD1 and NOD2 should be stimulated by the vast majority of bacterial infections." (PMID 33672738, 2021). "Travassos suggests that the sub-classes of the NLRs, NOD1, and NOD2 are essential for anti-bacterial infection by recruiting autophagy protein ATG16L1 to the plasma membrane at the bacterial entry site." (PMID 33013364, 2020). "Primary corneal fibroblast cells expressed NOD1 and NOD2, elevated NLRC4 after bacterial infection, but reduced NLRP1, NLRP3, NOD1, and NOD2 mRNA levels following LPS stimulation." (PMID 32019187, 2020). "The NLRs, are intracellular innate immune molecules including NOD1/CARD4 and NOD2/CARD15 proteins that are essential for innate immune responses to bacterial infections and tissue injury." (PMID 32578848, 2020). "In early endosomes, NOD1 interacts with peptidoglycan and RIP2, and promotes RIP2-dependent autophagy and inflammatory signaling in response to bacterial infection." (PMID 29692779, 2018). "Previous study showed that NOD1 can promote RIP2-dependent autophagy and inflammatory signaling on early endosomes in response to bacterial infection." (PMID 29692779, 2018). "The pattern recognition receptors NOD1 and NOD2 play an important role in the pro-inflammatory immune response to bacterial infections." (PMID 24960071, 2014).
bacterial infection (continued). "Therefore, it is conceivable that altered epithelial TLR4-mediated chemokine production caused by CsA, may potentiate the deleterious inhibitory effects of CsA on Nod1-mediated neutrophil functions, leading to a more pronounced decrease in host resistance to bacterial infection." (PMID 23382681, 2013). "Nevertheless, increasing numbers of recent reports suggest that NOD1 and NOD2 have important functions in non-bacterial infections." (PMID 23162548, 2012). "Although these NLRs share common signaling mediators to respond to bacterial infection and HFD consumption, the disparate roles of NOD1 and NOD2 in HFD mouse models suggest the use of novel and distinct signaling pathways by NOD1 and NOD2 downstream of RIP2 in the context of metabolic stress." (PMID 33503814, 2021). "We also observed induced protein and mRNA production such as NOD1, IL-10, MCP-1, NOD2, and RIP2 in RAW 264.7 cells under MOMP stimulation compared to normal cells, which are thought to be involved in various immune responses against bacterial infection." (PMID 34812410, 2021). "The results showed that NOD1 can identify LPS and activate the NF-κB signal pathway by recruiting RIPK2 and then promoting the expression of inflammatory cytokines to induce the resistance of organism against bacterial infection." (PMID 30013548, 2018). "Our data emphasize the protective nature of NLRP10 against microbial pathogens, thus adding NLRP10 to the group of NLR family members such as NOD1, NOD2, NLRC4, NLRP3, and NLRP12 that initiate pro-inflammatory signaling to mediate host resistance toward bacterial infections." (PMID 29163529, 2017). "Recently, study in miiuy croaker (Miichthys miiuy) showed that NOD1 can identify LPS and activate the NF-κB signal pathway by recruiting RIPK2 and then promoting the expression of inflammatory cytokines to induce the resistance of organism against bacterial infection." (PMID 30873182, 2019). "However, knockdown of both NOD1 and NOD2 impaired bacteria-induced activation of the NF-κB pathway in BLP-tolerised BMMs, as evidenced by significantly reduced nuclear translocation of p65 in response to bacterial infection." (PMID 28079153, 2017). "NOD1 and NOD2 receptors also respond to bacterial infections through an alternative pathway, independent of RIPK2 and NF-κB signaling." (PMID 30791886, 2019). "Although we found upregulated mRNA expression, we did not detect enhanced protein levels of NOD1 and NOD2 in BLP-tolerised BMMs after bacterial infection." (PMID 28079153, 2017). "Some of these feedback systems must involve the negative regulation of NOD1, NOD2 and RIG1, since these receptors are known to be activated by the viral and bacterial infections discussed here, yet they do not appear to be activated during cytokine release syndromes." (PMID 33672738, 2021). "Moreover, both NOD1 and NOD2 can activate autophagy during bacterial infection by a mechanism which is independent of RIP2 and NF-κB, by recruiting the autophagy protein ATG16L1 to the plasma membrane at the bacterial entry site." (PMID 30791886, 2019).
metabolic disease (7 papers, 2017 to 2024). A congenital disorder (due to inherited enzyme abnormality) or acquired (due to failure of a metabolically important organ) disorder resulting from an abnormal metabolic process. "It has been discovered that activated NOD1 is associated with the pathological mechanisms of certain metabolic diseases." (PMID 39906040, 2024). "These receptors play a role in recognizing bacterial pathogens, inducing liver inflammation, and have associations with innate immune activation in metabolic diseases, with studies suggesting that blocking NOD1 can be protective against tissue injury." (PMID 38719902, 2024). "Further studies are required to address how the crosstalks between NOD1 and other histone variants or bile acid receptors affect the occurrence of infectious diseases and/or metabolic diseases." (PMID 34356784, 2021). "Furthermore, it introduces the potential for NOD1 to serve as a risk assessment marker for metabolic diseases." (PMID 39906040, 2024). "This article provides a comprehensive review of the impact of NOD1 on metabolism across various tissues and organs, highlighting its potential significance in understanding metabolic disorders." (PMID 39906040, 2024). "This suggests that on balance the impact of NOD1 activation is a stronger influence on metabolic disease than the protective signals from NOD2." (PMID 37128291, 2023). "One mechanism proposed to drive activation of NOD1 or NOD2 in metabolic disease is excess nutrients generated during overfeeding conditions acting as endogenous ligands or danger-associated molecular patterns (DAMPs) to stimulate inflammation." (PMID 33503814, 2021). "Other studies demonstrate a selective upregulation of NOD1 in adipose tissue during metabolic disease." (PMID 33503814, 2021). "While this study only looked at the impact of a combined loss of NOD1 and NOD2, further studies have examined the requirement of these two receptors individually in the development of metabolic disease." (PMID 33503814, 2021). "However, when NOD1/2 double-knockout mice were studied they were protected from diet-induced metabolic disease including inflammation and insulin resistance, and showed lower lipid accumulation in WAT." (PMID 37128291, 2023). "Some studies of metabolic dysfunction using NOD1 and NOD2 deficient mice were conducted in germ-free mice, devoid of circulating peptidoglycan fragments, strongly supporting a role for circulating peptidoglycan in metabolic disease." (PMID 37128291, 2023). "In contrast, NOD1 signaling negatively influences metabolic disease." (PMID 37128291, 2023). "In addition to their classical roles as bacterial sensors, NOD1 and NOD2 have been implicated as mediators of metabolic disease." (PMID 33503814, 2021). "More recently, NOD1 and NOD2 have been implicated as mediators of human metabolic disease." (PMID 33503814, 2021). "Clinical studies have provided insight into whether NOD1 or NOD2 signaling is potentially altered in human metabolic disease." (PMID 33503814, 2021). "Taken together, these studies demonstrate that NOD1 activation may promote metabolic disease development, while the actions of NOD2 protect against the development of diet-induced metabolic disease in mouse models." (PMID 33503814, 2021). "Dietary fatty acids may be one of the key factors in the involvement of NOD1 in metabolic diseases." (PMID 39906040, 2024). "In addition to NOD1 and NOD2, NLRP3 activation is linked to more severe metabolic disease and bacterial peptidoglycan is a known activator of NLRP3, but experiments directly testing the impact of peptidoglycan on NLRP3-induced metabolic changes have not been reported and will require further study." (PMID 37128291, 2023). "Although the roles of NOD1 and NOD2 in metabolic diseases have been elucidated to some extent through animal models, further investigations are warranted to unravel the precise underlying mechanisms." (PMID 39329913, 2024).
metabolic disease (continued). "Although NOD1 and NOD2 share intracellular signaling pathway components, they are differentially upregulated on a cellular level and have opposing impacts on metabolic disease development in mouse models." (PMID 33503814, 2021). "Overall, these studies highlight the cell type specific responses of NOD1 and NOD2 that modulate ROS production and mitochondrial dysfunction that may contribute to metabolic disease." (PMID 33503814, 2021). "The activating stimuli for NOD1 and NOD2 in the context of metabolic disease are controversial and may be a combination of both metabolic and circulating bacterial ligands." (PMID 33503814, 2021). "The activating stimuli for NOD1 and NOD2 in the context of metabolic disease is controversial and may be a combination of metabolic and bacterial ligands, as well as involve direct and indirect mechanisms of action." (PMID 33503814, 2021). "Taken together, these studies link aberrant NOD1 and NOD2 expression and activation, rather than genetic variants, with metabolic diseases." (PMID 33503814, 2021). "Finally, many of the proposed roles for NOD1 and NOD2 in metabolic disease have been defined in animal models and require more extensive investigation in larger studies of human metabolic disease." (PMID 33503814, 2021). "Overall, there is not currently strong evidence of a genetic link of either NOD1 or NOD2 polymorphisms and the development of human metabolic disease." (PMID 33503814, 2021). "Similarly, the nature of the NOD1 and NOD2 activating signals in the context of metabolic disease is yet to be conclusively defined with studies indicating the existence of circulating factors, which could be dietary or microbial (or a combination of both) that activate these NLRs." (PMID 33503814, 2021). "Evidence suggests that NOD1 and NOD2 play both positive and negative roles in ROS generation and subsequent mitochondrial dysfunction that may mediate the pathogenesis of metabolic disease." (PMID 33503814, 2021).